ZEB1 (zinc finger E-box binding homeobox 1)
Diseases named in the same sentence as ZEB1 in open-access papers (continued):
Sharing a sentence is not in itself a finding about the gene and the disease.
breast carcinoma (continued). "The EMT inducing transcription factor ZEB1 also facilitates conversion of CD44low breast cancer cells into a CD44hi CSC state." (PMID 27608848, 2016). "Since ZEB1 is also expressed in tumour stromal cells, we analysed expression in cancer cells by immunohistochemistry of human breast cancers and also considered protein localization." (PMID 26876920, 2016). "Together, these findings support the idea of using epigenetic suppression of ZEB1 as a novel therapeutic strategy to help overcome drug resistance in human breast cancer." (PMID 26646320, 2016). "Given that the VEGF family members are potent modulators of angiogenesis and metastatic growth in the pathophysiology of breast cancer, we further confirm the regulation of ZEB1 on VEGFs secretion by Western blotting and ELISA." (PMID 26882471, 2016). "GPC3 induces MET through ZEB1 pathway, and controls growth, death, migration and metastatic spread of breast cancer cells." (PMID 27507057, 2016). "On the basis of these results, we propose a model in which elevated expression of ZEB1 in breast cancer cells activates the secretion of VEGFA protein and creates a chemotactic gradient to promote angiogenic stimulation." (PMID 26882471, 2016). "In this study, we showed that ectopic expression of ZEB1 resulted in significant upregulation of VEGFA synthesis in MDA-MB-231 breast cancer cells, thus promoting tumor angiogenesis in vitro and in vivo." (PMID 26882471, 2016). "Although zinc finger E-box binding homeobox 1 (ZEB1) has been identified as a key factor in the regulation of breast cancer differentiation and metastasis, its potential role in modulating tumor angiogenesis has not been fully examined." (PMID 26882471, 2016). "The pro-angiogenic activity of ZEB1 is consistent with previous reports that an increased ZEB1 level is observed in advanced human breast cancer tissue." (PMID 26882471, 2016). "Collectively, these data demonstrate that ZEB1 has the capacity to induce the formation of new blood vessels in vivo, and thus facilitates tumorigenesis in breast cancer." (PMID 26882471, 2016). "Genes of the common ZEB1/YAP target gene set were highly expressed in breast cancer cell lines assigned to the claudin-low and basal B subtype." (PMID 26876920, 2016). "Silencing ROR1 expression by siRNA reduces the expression of EMT-associated proteins, such as SNAIL-1/2, ZEB1, CXCR4, and vimentin in breast cancer cell line MDA-MB-231." (PMID 27830754, 2016). "Using a nude mouse xenograft model, we demonstrated that elevated expression of ZEB1 promotes in vivo tumorigenesis and angiogenesis in breast cancer." (PMID 26882471, 2016). "Consistently, we have shown that ZEB1 is central in inducing EPB41L5 in breast cancer cells and renal cancer cells." (PMID 27871329, 2016). "The authors show that ZEB1 overexpression in breast cancer cells recruits Sp1 to VEGFA promoter region and activates VEGFA expression and secretion, therefore promoting angiogenesis in vitro and in vivo." (PMID 27411336, 2016). "During the metastasis, epithelial-to-mesenchymal transition (EMT) is essential and Snail, Claudin-1 and ZEB1 are well-known markers for metastasis in breast cancer." (PMID 27625789, 2016). "Tumor volumes and weights in mice injected with ZEB1/231 cells were significantly higher than in those injected with Control/231 cells, consistent with our previous study that ZEB1 promotes tumorigenesis of breast cancer." (PMID 26882471, 2016). "Transient overexpression of ZEB1 in MCF7 breast cancer cells revealed concentration dependent upregulation of BMP-inhibitors." (PMID 25973542, 2015). "Indicating clinical relevance, MYLK and TKS5 levels also correlate positively with ZEB1-, but negatively with E-cadherin and miR-200-levels in human breast cancer samples." (PMID 26334100, 2015). "Positive nuclear ZEB1 expression was observed in epithelial cells of breast cancer tissues confirming that NOM and OSCC inherently do not express this transcription factor." (PMID 26214683, 2015).
breast carcinoma (continued). "Next, we investigated the effect of miR-34a mimic and inhibitor on HNK-induced cytoplasmic retention of Zeb1 in breast cancer cells." (PMID 26359358, 2015). "Taken together, the data indicated that ZEB1 regulates the expression of secreted BMP-inhibitors in bone metastatic breast cancer cells, thereby inducing the differentiation of osteoclasts." (PMID 25973542, 2015). "Recently published work suggests that Zeb1 is the most proximal EMT transcription factor in breast cancer, acting via the repression of E-cadherin and the microRNA-200 family." (PMID 25528765, 2015). "The ectopic expression of miR-33b downregulated the expression of ADAM9, HMGA2, LDHA, SALL4, SNAI2 and Twist1 by more than 30% but had minimal effects on HIF-1α, RAC1, Yes1 and ZEB1 in these two breast cancer cell lines." (PMID 25919570, 2015). "In the present study we provide further evidence for the role of ZEB1 during breast cancer bone metastasis since we found a published gene set upregulated in bone metastases to be enriched with genes positively regulated by ZEB1." (PMID 25973542, 2015). "Co-expression of both genes with ZEB1 was observed in several cancer cell lines as well as in breast cancer patients and correlated with low miR-200c levels." (PMID 26334100, 2015). "To examine the functional impact of the LPA1/ZEB1/miR-21 pathway on the metastatic activity of LPA on basal breast cancer cells we carried out wound healing migration assays and matrigel invasion assays." (PMID 26098771, 2015). "Here we identify a set of genes that is highly expressed in breast cancer bone metastasis and activated by ZEB1." (PMID 25973542, 2015). "More importantly, the expression of lnc-ATB was significantly associated with ZEB1 and ZNF217 expression in TR breast cancer patients." (PMID 25871474, 2015). "Alteration in the expression of E-cadherin and ZEB1 lend additional evidence in support of the potential of glyceollin to reverse EMT in letrozole resistant breast cancer cells." (PMID 26703648, 2015). "We then extracted the LPAR1 and ZEB1 expression data from 51 human breast cancer cell lines from the publically available database GSE12777, classified into basal (n = 24) and non basal subtypes (n = 27)." (PMID 26098771, 2015). "Many transcriptional repressors, such as Snail, Slug, Twist, ZEB1, ZEB2, have been implicated in the regulation of EMT for a variety of cancers, including breast cancer, colon cancer, liver and HNSCC." (PMID 25749385, 2015). "It has been shown that the zinc finger E-box binding homeobox 1 (ZEB1) transcription factor plays a critical role in EMT in breast cancer." (PMID 26703648, 2015). "The expression of EMT markers, including CDH1, CDH2, VIM, ZEB1 and ZEB2, is associated with poor prognosis of breast cancer patients." (PMID 26062653, 2015). "Western blot analyses were also performed and ZEB1 protein expression results directly correlated with ZEB1 gene expression suggesting that glyceollin I alters critical regulators of EMT in letrozole resistant breast cancer cells." (PMID 26703648, 2015). "The transcription of miR-200 family members (miR-141 and miR-200c) is suppressed by ZEB1, which activates epithelial differentiation in PC, colorectal, and breast cancer cells." (PMID 26516699, 2015). "It has been confirmed down-regulation of miR-200c promote invasiveness and EMT of breast cancer by regulating the expression of ZEB1 and ZNF217." (PMID 25871474, 2015). "We have demonstrated that ZEB1 expression is crucial for expression of BMP-inhibitors in breast cancer cells both by directly increasing their gene transcription and by indirectly suppressing their reduction via miR-200 family members." (PMID 25973542, 2015). "This seems to be reflected by our observation that ZEB1 mediated regulation of BMP-inhibitors differs between parental breast cancer cell lines and the bone metastatic MDA-BoM-1833 cells." (PMID 25973542, 2015).
breast carcinoma (continued). "An endothelial to mesenchymal transition-like process was described in lymphendothelial cells during the intravasation of breast carcinoma cells involving the function of EMT inducer ZEB1." (PMID 25742314, 2015). "We then compared the resulting 173 in silico candidates with expression array data of the mesenchymal/undifferentiated mammary cancer cell line MDA-MB-231 (shCtrl) in comparison to ZEB1 knockdown cells (shZEB1)." (PMID 26334100, 2015). "The AP1-complex members c-JUN and c-FOS are involved in the activation of the promoter of MMP1 in MDA-MB-321 breast cancer cells secondary to the activation of ZEB1, a transcription factor involved in EMT." (PMID 24586640, 2014). "The observations made in this investigation show that SK228 reverses the EMT process in breast cancer cells via an effect on the miR-200c/ZEB1/E-cadherin signalling pathway." (PMID 24967704, 2014). "Three human breast cancer cells, which have been reported to express very low levels of E-cadherin and high levels of ZEB1, were employed in a study designed to probe this issue." (PMID 24967704, 2014). "Other work has shown that MUC1-C induces EMT in breast cancer cells by activating the ZEB1/miR-200c regulatory loop." (PMID 24770886, 2014). "Specifically, ZEB1 results downregulated in our breast cancer dataset compared to normal samples, while both the mir-200 family members and CDH1 are overexpressed." (PMID 25033876, 2014). "Considering ZEB1 is a transcription factor that can either activate or repress its target genes, we think it functions differently in breast cancer cell lines and breast cancer patients." (PMID 25394902, 2014). "Concerted downregulation of all five members of the miR-200 family by TGF-β in human breast cancer cells derepressed the miR-200 target genes, ZEB1 and P 1, mediating repression of E-cadherin EMT and tumor cell invasiveness." (PMID 24086574, 2013). "In endocrine-sensitive luminal breast cancer cells, expression of miR-200 family members represses ZEB1, thus E-cadherin is expressed and vimentin is repressed and cells have an epithelial phenotype." (PMID 23626803, 2013). "Collectively our data link the transcriptional regulation of MYB by ZEB1 to the proliferative state of cells during EMT-MET in breast cancer, and also indicate a contribution of MYB to the epithelial phenotype." (PMID 24283570, 2013). "The current study sought to determine the ZEB1/MYB/proliferation interplay in the epidermal growth factor (EGF)-responsive PMC42 model of breast cancer EMT." (PMID 24283570, 2013). "It is known that the feedback loop model links ZEB1 to miR-200c in melanoma and breast cancer cells, and that ZEB1 and miR-200c repress each other in the loop that impacts the change in EMT-MET." (PMID 23842108, 2013). "In a breast cancer cell line, ZEB1 expression is dependent on NF-κB, which is constitutively activated in cancer and stromal cells of breast cancers, and promotes EMT and cell survival." (PMID 23565224, 2013). "We therefore compared the expression pattern of miR-200b eRNA with miR-200b~200a~429 gene cluster and other epithelial (E-Cadherin) and mesenchymal (ZEB1) genes in a panel of breast cancer cell lines." (PMID 24086551, 2013). "For example, overexpression of miR-200b and miR-200c caused MET in mesenchymal breast cancer cell lines MDA-MB-231 and BT549 by repressing ZEB1 and ZEB2." (PMID 23626803, 2013). "We selected 10 genes for the confirmation study based on their potential roles in breast cancer and ZEB-1 was used as a control." (PMID 23497265, 2013).
breast carcinoma (continued). "ZEB1 was identified first as a strong predictor of poor survival and distant metastasis in colorectal adenocarcinoma, breast cancer, and lung adenocarcinoma." (PMID 23690952, 2013). "miRNA 200c, which suppresses Zeb-1, thereby inducing an epithelial phenotype, has been transfected into bladder, ovarian, and breast cancers, leading to restoration of chemosensitivity." (PMID 23543898, 2013). "MDA-MB-231 cells are metastatic breast cancer cells that express multiple zinc finger transcriptional repressors, including Snai1, Snai2, Zeb1 and Zeb2, all of which can bind Eboxes in the E-cadherin promoter and regulate EMT." (PMID 22393397, 2012). "Consistent with the inhibition of invasion, CHD5 down-regulated mesenchymal markers vimentin, N-cadherin and ZEB1 in breast cancer cells." (PMID 22569290, 2012). "Of note, endogenous expression of the Zeb1, Zeb2 and Twist2 EMT inducers was also induced, further supporting the association of the EMT interactome with the claudin-low breast cancer subtype." (PMID 22654675, 2012). "ERβ1 was found to induce the expression of E-cadherin by inhibiting its transcriptional repressors ZEB1/2 and up-regulating the miR-200a, miR-200b and miR-429, which correlate with the epithelial breast cancer phenotype." (PMID 23158001, 2012). "ZEB1 mRNA is also induced by progesterone in the human T47D breast cancer cell line, in human myometrial cells, and in mouse uterus, indicating that expression of ZEB1 is steroid-regulated in a variety of tissues." (PMID 22190929, 2011). "Our analysis of Affymetrix expression data from 51 human breast cancer cell lines also show Zeb1/δEF1 to correlate most tightly with the mesenchymal/BasalB subgroup." (PMID 19604397, 2009). "This has been shown functionally in the progression of breast carcinomas, where Snail1 is necessary for initial invasion, and Zeb1/δEF1 and other E-cadherin repressor genes are involved in the maintenance of the mesenchymal phenotype, including motility." (PMID 19604397, 2009). "One probeset for Zeb1/δEF1 demonstrated differential expression in regards to disease recurrence/death from breast cancer (Mann-Whitney test, p = 0.026)." (PMID 19604397, 2009). "Therefore, ZEB1 promotes hypermethylation of the ERα promoter, leading to estrogen inhibitor resistance in breast cancer." (PMID 40843360, 2025). "ZEB1 expression rises in breast cancer and is positively correlated with levels of ATM protein." (PMID 40843360, 2025). "We found that the transcription factor Zeb1 promoted circLRBA expression in breast cancer cells." (PMID 41082269, 2025). "Indeed, ZEB1 is a major driver of radioresistance in breast cancer and plays a role in radiation resistance in several other cancers including prostate, colon and stomach cancers." (PMID 40275610, 2025). "In breast cancer, for example, the delivery of miR-200c-3p using tumor-targeted nanoparticles has shown promise in inhibiting tumor growth and metastasis by downregulating oncogenes like ZEB1 and ZEB2." (PMID 39859424, 2025). "Additionally, Zeb1-induced CSC properties in breast cancer cells were reduced after the expression of neurogenin-3, which is a gene known to be repressed by Zeb1." (PMID 40806166, 2025). "Moreover, in breast cancer cells, miR-223 inhibits the proliferation and migration of cells by inhibiting the expression of ZEB1." (PMID 38164285, 2024). "Moreover, the Gene expression-based Outcome for Breast cancer Online dataset showed that TNBC cell lines expressed a higher average of AhR and ZEB1 expression compared with that in hormone receptor–positive HER2+ breast cancer cell lines." (PMID 39311710, 2024). "On the contrary, high expression of ZEB1 is related to poor prognosis of breast cancer patients." (PMID 38164285, 2024). "Moreover, aggressive tumors with an EMT phenotype often exhibit high expression of PD-L1 indirectly induced by ZEB1, resulting in immunosuppression in breast cancer." (PMID 39256881, 2024).
breast carcinoma (continued). "The expressions of NOTCH3 and ZEB1 are negatively correlated in breast cancer." (PMID 38164285, 2024). "This downregulation of OPG in breast cancer cells was accompanied with an increase in the expression of the ERα protein and the epithelial markers E-cadherin and EpCAM, while the mesenchymal markers N-cadherin, Snail, and ZEB1 were downregulated." (PMID 39181873, 2024). "ZEB1 plays a key role in tumor progression, metastasis, invasion and treatment resistance 28, 29, as well as in regulating the differentiation and metastasis of breast cancer." (PMID 38164285, 2024). "For example, SNHG3 which was involved in the miR-186-5p/ZEB1 pathway could mediate pathological invasion and metastasis as well as transforming breast cancer cells into epithelial-mesenchymal." (PMID 38960931, 2024). "Our results show that miR-223 can regulate the expression of ZEB1 in breast cancer cells." (PMID 38164285, 2024). "However, further experimental design and research are needed to verify the effect of NOTCH3/miR-223/ZEB1 axis on breast cancer at the animal and clinical levels." (PMID 38164285, 2024). "This investigation further describes the possible role of NOTCH3/miR-223/ZEB1 in breast cancer." (PMID 38164285, 2024). "Studies have shown that B3GALT5 is upregulated in breast cancer and can regulate the expression of zinc finger E‐box binding homeobox transcription factor 1 (ZEB1) as well as the activation of β‐catenin nuclear translocation, promoting the progression of breast cancer metastasis." (PMID 39224045, 2024). "Multiple EMT-inducing transcription factors, such as TWIST1, SNAIL1/2, and ZEB1/2, may be expressed to drive breast cancer cells to undergo EMT and produce increased invasion, metastasis, and resistance to therapies, including immunotherapy." (PMID 38893094, 2024). "Furthermore, the average of the expression of TDO2, AhR, and ZEB1 genes is higher in basal-like breast cancer (TNBC) than that in luminal A/B [estrogen receptor–positive (ER+)] breast cancer and when generally comparing ER− versus ER+ tumors." (PMID 39311710, 2024). "Similarly to the immunofluorescence data, the RT-qPCR results revealed that Zeb1 expression markedly decreased in breast cancer cells when PNKY was suppressed." (PMID 37104007, 2023). "Additionally, it maintains and restores the epithelial morphology of breast cancer cells by downregulating ZEB1 transcription, thereby preventing EMT in breast cancer." (PMID 37771431, 2023). "As shown here, the parental M13SV1-EGFP-Neo breast epithelial cells and HS578T-Hyg breast cancer cells, as well as their M13HS tumor hybrids and the ZEB1-KO variants exhibit different colony and mammosphere formation capacities and migration/invasion properties." (PMID 38139138, 2023). "We further found that PNKY may trigger EMT in breast cancer cells by upregulating miR-150 and restricting the expression of Zeb1 and Snail." (PMID 37104007, 2023). "In addition, ETS2 、ERαand Sp1, KLF4, and ZEB1/YAP have also been identified as regulators of hTERT transcription in breast cancer cells." (PMID 37612721, 2023). "A study on breast cancer showed that TRIP12 suppresses EMT via ZEB1/2." (PMID 37573347, 2023). "Further analysis of the novel ZEB1 heterodimer complex with ZEB2 may open a pathway to elucidate the uncovered functions of ZEB1 in breast cancer progression." (PMID 36910659, 2023). "Therefore, we believed that GPR176 knockdown promoted pyroptosis and suppressed the EMT of breast cancer by increasing the levels of Zeb1, Slug, Snail, and Twist1." (PMID 37079213, 2023). "Due to their solid digesting function, the matrix metalloproteases MMP1, MMP11, MMP14, and MMP16 might confer invasiveness to breast cancer cells through the Zn2+-bound ZEB1." (PMID 36910659, 2023).